CXCL2 (C-X-C motif chemokine ligand 2)
Diseases named in the same sentence as CXCL2 in open-access papers (continued):
Sharing a sentence is not in itself a finding about the gene and the disease.
Sepsis (46 papers, 2010 to 2026). Sepsis is defined as life-threatening organ dysfunction caused by a dysregulated host response to infection. "Firstly, XBJ effectively reversed lung injury caused by sepsis and restrained neutrophils recruitment to lung by down-regulating proinflammatory chemokines, such as CSF-3, CXCL-2, and CXCR-2." (PMID 36467039, 2022). "This peritoneal vicious cycle that includes NET formation, IL-17A, CXCL-1/CXCL-2 that may amplify sepsis-associated organ injury." (PMID 41588042, 2026). "Interestingly, a CXCL2 tandem repeat promoter polymorphism is associated with susceptibility to severe sepsis." (PMID 36278756, 2022). "CXCL2 which is an essential mediator in lung protection but polymorphism of a short tandem repeat (AC)n at -665 position in the promoter region altered the promoter's activity, consequently heightened the expression of CXCL2 thus contributing to severe sepsis." (PMID 28989790, 2017). "However, the adoptive transfer of WT resident cells into MyD88-deficient mice before the induction of sepsis resulted in the increase of local levels of CXCL2." (PMID 25084278, 2014). "The expression of CXCL2 is noteworthy because it is consistently up-regulated in early sepsis when compared to healthy individuals, and polymorphisms in this gene have been associated with outcomes in severe sepsis." (PMID 24667684, 2014). "In addition, CXCL2 is also involved in renal I/R injury and sepsis-associated acute kidney injury." (PMID 34338139, 2021). "Another study demonstrates that the circadian factor BMAL1 regulates innate immunity in sepsis and protects against sepsis-induced ALI by suppressing CXCL2 expression." (PMID 40806591, 2025). "In sepsis, the chemokine CXCL2 and its receptor CXCR2 play a critical role in neutrophil and monocyte recruitment and promotes their migration to inflammatory sites." (PMID 40977737, 2025). "CXCL2, also known as macrophage inflammatory protein-2 (MIP-2), is associated with the severity of sepsis." (PMID 40520010, 2025). "C-C chemokine ligand 2 (CCL2), C-X-C chemokine ligand 8 (CXCL8)/IL-8, and CXCL2 have been widely studied in sepsis-induced myocardial injury." (PMID 40520010, 2025). "In the present study, we found CXCL2 expression was upregulated in the hippocampus tissue, blood serum, microglia and medium supernatant after sepsis/LPS stimulus." (PMID 40115159, 2024). "In this study, we also found that CLP-induced sepsis obviously upregulated the expression of Jun in hippocampus tissue, whereas the increasing tendency suffered a reversal after CXCL2 knockdown." (PMID 40115159, 2024). "In this study, we reveal a previously unproven phenomenon and mechanism in which sepsis-activated microglia induces the occurrence of neuronal ferroptosis via the CXCL2/CXCR2/Jun axis." (PMID 40115159, 2024). "For example, blocking S100A9 with the inhibitor ABR-238901 greatly attenuates the CLP-induced infiltration of neutrophils, formation of edema, and expression of Mac-1, CXCL1, CXCL2 and IL-6 in the plasma or lung and improves sepsis-induced lung injury." (PMID 36768433, 2023). "HU-308 has been reported to reduce plasma CXCL1, CXCL2, and TNFα in rodent models of sepsis, hepatic injury, and nephropathy." (PMID 36555499, 2022). "The administration of CXCL2 immediately after sepsis induction increases peritoneal neutrophil recruitment and survival of septic mice." (PMID 36278756, 2022). "Consistently, in our previous study, we demonstrated that XBJ significantly down-regulated the expression of CXCL-2 in sepsis-induced cardiac dysfunction." (PMID 36467039, 2022). "We evaluated the plasmatic release of TNFα and CXCL2/3 in wild-type animals during polymicrobial sepsis to strengthen our findings." (PMID 34948374, 2021). "In the present study, we found that ABR-238901 attenuated sepsis-associated CXCL1 and CXCL2 formation by more than 50% and 38% in the lung." (PMID 34884728, 2021).
Sepsis (continued). "In summary, Paeoniflorin and HSYA are key active compounds in XBJ for managing sepsis, protecting cardiac function, and controlling inflammation in the cardiac tissue partially by limiting the production of IL-6, IL-1β, and CXCL2." (PMID 33986658, 2020). "Two studies revealed that CXCL2 polymorphism is related to the severity of sepsis in patients, suggesting CXCL2 playing an important role in the development of severe sepsis." (PMID 33986658, 2020). "In fact, this has been implied in our previous work that demonstrated plasma EVs isolated from sepsis mice promoted significant CXCL2 and IL-6 via miRNA- and TLR7-dependent mechanisms." (PMID 32958516, 2020). "Congruently, administration of the neutrophil attractants CXCL1 and CXCL2 into the peritoneal cavity after inducing polymicrobial sepsis enhances both neutrophil recruitment and clearance of bacteria, as well as improving host survival." (PMID 28405616, 2017). "Treatment with Smaducin-6 also reduced the level of CXCL2 chemokine, one of the hallmarks of sepsis." (PMID 25766838, 2015). "In agreement with the neutrophil recruitment data, CXCL1 and CXCL2 levels were similar in the three experimental groups in all tested time points after severe sepsis induction." (PMID 25084278, 2014). "CLP-induced sepsis resulted in a significantly higher CXCL-2 level in vehicle-treated mice compared to the sham group." (PMID 21188216, 2010). "Recent research employs CXCL2 chemokine as an intermediary in sepsis treatment." (PMID 41378129, 2025). "This peritoneal vicious cycle that includes NET formation, IL-17A, CXCL-1/CXCL-2 that may amplify organ injury in sepsis." (PMID 41041553, 2025). "Many literatures have indicated that CXCL2 is involved in the progression and prognosis of sepsis." (PMID 40115159, 2024). "Furthermore, a recent original study revealed that macrophagic extracellular vesicle CXCL2 can aggravate the progression of sepsis via recruiting and activating the neutrophil CXCR2/PKC/NOX4 axis." (PMID 40115159, 2024). "Increased values for IL-1β, IL-6, IL-10 and CXCL-2 were also observed in all volatile anesthetic sepsis groups compared to isoflurane-sham animals (all P <0.03), and IFN-γ was increased in isoflurane + CLP compared to isoflurane-sham animals (134.2 ± 131.9 versus 12.4 ± 12.2 pg/ml, P = 0.04)." (PMID 25887642, 2015). "Despite the reduction in the neutrophil recruitment in MyD88-deficient mice 6 h after severe sepsis induction was not significant, these mice showed diminished CXCL2 levels at the infection site under this severity of sepsis." (PMID 25084278, 2014). "Notably, gene expression of in particular CXCL2 was further enhanced by combined stimulation of hepatocytes with bile acids and IL-1β, highlighting the role of bile acids as DAMPS in the context of sepsis-associated cholestasis." (PMID 39680527, 2024). "However, whether sepsis-activated microglia can secrete CXCL2 and thus promote the neuronal ferroptosis remains unclear." (PMID 40115159, 2024). "The results showed that the levels of Tnfα, IL-1β, CXCL2, CXCL10, CCL2, and CCL3 increased significantly in response to sepsis sEVs compared with healthy sEVs." (PMID 38910259, 2024). "As sepsis is a systemic intravascular infectious disease, during sepsis, the endothelial cells in the cerebrovascular blood vessels also produce various chemokines, such as CCL2, CCL3, CCL5, CXCL1, CXCL2, CX3CL1, and CXCL8." (PMID 38585633, 2024). "In macrophages, the most differentially expressed genes after sepsis include S100a9, S100a8, Hbb-bs, Fth1, AW112010, Spic, Cxcl2, Cd14, Hmox1, and Vcam1." (PMID 38343542, 2024). "In polymicrobial sepsis, the activation of the NFAT pathway led to an increase in the expression of chemokines (CXCL1, CXCL2 and CXCL5) and neutrophil migration and infiltration in the lung, whereas FK506 impaired central migration of neutrophils." (PMID 38242872, 2024).
Sepsis (continued). "Regarding neutrophils, the levels of Tnfα, IL-6, IL-1β, CXCL1, CXCL2, CCL5, and CXCL10 increased significantly in response to sepsis sEVs compared with those from the control group and healthy individuals." (PMID 38910259, 2024). "In addition, human CXCL2 can synergize with granulocyte colony-stimulating factor to rapidly mobilize the bone marrow early hematopoietic stem and progenitor cells, which may promote liver regeneration and enhance the immune function in sepsis." (PMID 39619227, 2023). "Mice with LPS-induced-sepsis who were treated with BPF had lower serum levels of IL-6, TNF-α, IL-1β, CXCL1, and CXCL2 than the control mice treated with BPF." (PMID 36361915, 2022). "Some studies have shown that the levels of characteristic cytokines such as TNF‐α, IL‐6, IL‐1β, IL‐1α, IL‐12, IL‐17, CXCL1, CXCL2, MCP‐1, IL‐8, CXCL10, GM‐CSF, M‐CSF, and G‐CSF in patients with septicemia are significantly higher than those in normal volunteers." (PMID 36684101, 2023). "In the setting of sepsis, the locally produced chemokines, such as CXCL1, CXCL2, and CXCL6, could lead to neutrophil chemotaxis and subsequent neutrophil infiltration by ligand-receptor binding." (PMID 35345558, 2022). "A previous study showed that blocking CXCR2, the main receptor of CXCL1 and CXCL2, effectively decreased alveolar accumulation of neutrophils in the CLP model of sepsis, demonstrating that CXC chemokines are important regulators of pulmonary infiltration of neutrophils in septic lung injury." (PMID 34884728, 2021). "This could be explained by the fact that sepsis induces eCIRP release into the lungs, which activates ATII cells to release cytokines and chemokines, such as IL-6 and CXCL2, resulting in a subsequent infiltration of neutrophils into the lung tissue causing ALI." (PMID 32984356, 2020). "Also, the chemokines, CCL-2, CXCL-2, and cytokines, IL-1β and IL-6, were not affected by NK-2R blocking in sepsis." (PMID 21188216, 2010). "Moreover, CXCL2 levels were also similar 6 hours after non-severe sepsis induction." (PMID 25084278, 2014). "During non-severe sepsis, neutrophils expressing C-X-C Motif Chemokine Receptor 2 (CXCR2) are recruited from the blood to the site of infection in response to C-X-C Motif Chemokine Ligand 2 (CXCL2) and other chemoattractant." (PMID 34200950, 2021).
melanoma (39 papers, 2007 to 2025). A malignant, usually aggressive tumor composed of atypical, neoplastic melanocytes. "Treatment with the anti-tumor drug Decarbazine (DTIC) reduced melanoma cell migration by decreasing protein concentrations of the migrating chemokines CXCL2 and CXCL11." (PMID 40429702, 2025). "Intriguingly, while CXCL2 was expressed by fibroblasts from all skin cancer types, melanoma-derived CAFs expressed high levels of CXCL1-3, 5, 6 and 8 and IL1B as well as IL6, whereas the expression of CXCL9-11 and 13 was high in non-melanoma CAFs." (PMID 39516494, 2024). "Analysis of different melanoma data suggested that CXCL2, 12, and 14 were particularly high in melanoma." (PMID 38525245, 2024). "Given that VEGFA, TGFβ1, CCL5 and CXCL2 are released in cell media (CM) as soluble factors, we collected the supernatants from drug resistant A375 and M14 melanoma cells and from their sensitive counterparts." (PMID 36418472, 2023). "Among them, we found that CXCL2 cDNA-incorporated HVJ-E enhanced anti-tumor immunity in a mouse melanoma model by increasing N1-type TANs." (PMID 33575480, 2021). "Further dissection of cluster 1 induced in IL-32–treated tumors showed significantly increased protein levels of the CCR5-binding chemokines CCL3, CCL4, CCL5, and CXCL2, corroborating the observations in IL-32hi human melanoma." (PMID 32841222, 2020). "The combination of HVJ-E with recombinant CXCL2 protein or CXCL2-expressing plasmid DNA dramatically decreased melanoma growth via CTL activation against melanoma." (PMID 27259252, 2016). "HVJ-E in combination with recombinant CXCL2 protein or CXCL2 pDNA suppressed mouse melanoma by increasing cytotoxic T lymphocyte activity against B16-F10 melanoma, which was abolished by an anti-Ly6G antibody." (PMID 27259252, 2016). "Because HVJ-E was originally developed as a gene delivery vector, we attempted to perform gene therapy against melanoma using an HVJ-E containing the CXCL2 gene." (PMID 27259252, 2016). "For instance, expression of CCL3, CCL5 and CXCL2 in melanoma-treated DRG cells increased up to 3.5-, 4- and 3-fold, respectively, compared to control DRG cells (p<0.05, n = 3)." (PMID 27227315, 2016). "While both markers were increased in senescent NHEM and melanoma cells, a statistical significance could only be detected for CXCL2." (PMID 35563794, 2022). "In contrast, it reduces the expression of CXCL1 and CXCL2 in WM793B melanoma cells." (PMID 33467722, 2021). "They concluded that blockade of CXCL1 and CXCL2 could improve immune tolerance at the tumor site by decreasing MoMDSCs in melanoma." (PMID 32707850, 2020). "Next, to test whether either CXCL1 or CXCL2 was necessary for enhancing the anti-tumor effects of HVJ-E, an anti-CXCL1 or CXCL2 antibody was intratumorally injected into melanoma-bearing mice 24 hours before the injection of HVJ-E+poly I:C." (PMID 27259252, 2016). "We hypothesized that the combination of HVJ-E and CXCL2 might exert similar anti-tumor effects via anti-tumorigenic neutrophils in melanoma tissues." (PMID 27259252, 2016). "Thus, EPHA2 and CXCL2 potential role in cycling hypoxia-induced melanoma progression is worth further investigation." (PMID 25122487, 2014). "CXCL2 was induced by cycling hypoxia in ovarian cancer cells and repressed in melanoma." (PMID 25122487, 2014). "Finally, we observed a significant negative Spearman correlation (r = −0.4021; p = 0.0376) between the two Down-miRs (i.e. miR-204-5p and miR-199b-5p) and the four Up-genes (i.e. VEGFA, TGFβ1, CCL5 and CXCL2) only in melanoma biopsies progressed after targeted therapies (PD samples)." (PMID 36418472, 2023). "These included Il10, Ccl2, and Cxcl2, which are also up-regulated in response to SHP2 inhibition in melanoma." (PMID 40992926, 2025). "In human melanoma biopsies, CXCL1/Groα and CXCL2/Groβ genes were over-expressed in metastatic patient samples compared to non-metastatic ones." (PMID 37525065, 2023).
melanoma (continued). "Melanoma cells constitutively released CXCL8/IL-8, CXCL1/Groα and CXCL2/Gro-β, and CM induced PMN chemotaxis was dependent on CXCR1/2 activation." (PMID 37525065, 2023). "Neutrophils of the tumour inflammatory infiltrate increase during melanoma progression, their accumulation depending on CXCL1, CXCL2, CXCL3, CXCL5, and CXCL8 molecules, which are stimulated by UV radiations." (PMID 35334544, 2022). "Based on the GEPIA analysis 30, high level of CXCL1, CXCL2 and CXCR2 genes indeed often predicted the poor prognosis in melanoma patients." (PMID 35265199, 2022). "CXCL2 and CXCL8 have been correlated to cancer cells chemoresistance, migration, angiogenesis and progression in melanoma, colon and ovary cancers." (PMID 34038868, 2021). "The chemokines belonging to the growth-related oncogene (GRO) subgroup of CXC chemokines, GRO-α/CXCL1, GRO-β/CXCL2, GRO-γ/CXCL3, were first identified as growth factors of melanoma cell lines, before being attributed neutrophil chemotactic activity." (PMID 34503058, 2021). "The expressions of both CXCL1 and CXCL2 are increased by chronic hypoxia in PC-3 prostate cancer cells but reduced in SK-OV-3 ovarian adenocarcinoma and WM793B melanoma cells." (PMID 33467722, 2021). "Upregulation of CXCL1, CXCL2, and CXCL8 mRNA in A-375 and SKMEL-28 melanoma sEVs was the most consistent finding." (PMID 30870978, 2019). "In this study, we were able to correlate the expression of the most consistently upregulated A-375 and SKMEL-28 melanoma sEV mRNAs (CXCL1, CXCL2, and CXCL8) to CXCL1, CXCL2, and particularly CXCL8 protein production at the sEV source cell level." (PMID 30870978, 2019). "Increased CXCL1, CXCL2, and CXCL8 mRNA in melanoma sEVs, relative to primary melanocyte sEVs, was the most consistent finding." (PMID 30870978, 2019). "Upregulation of pro-angiogenic chemokine ligand CXCL1, CXCL2, and CXCL8 mRNAs in A-375 and SKMEL-28 melanoma sEVs was the most consistent finding." (PMID 30870978, 2019). "Neutrophils migrate into melanoma using the CXCR2 chemokine receptor in response to its ligands CXCL1, CXCL2, and CXCL5 expressed in melanoma." (PMID 30899263, 2019). "The results demonstrate significantly increased production of CXCL1, CXCL2, and CXCL8 protein by A-375 melanoma cells compared to primary melanocytes." (PMID 30870978, 2019). "Among these, CXCL1, CXCL2, and CXCL5 can bind to chemokine receptor CXCR2, which is expressed on several melanoma cell lines and mediates signaling to significantly facilitate their growth in vitro and in vivo." (PMID 29541408, 2018). "GRO chemokines that are expressed during melanoma tumours, and are essential for wound healing activities, comprise three highly similar proteins known as GRO-α (CXCL1), GRO-β (CXCL2) and GRO-γ (CXCL3)." (PMID 28989790, 2017). "Presented here analysis demonstrated that melanoma cells secrete different levels CXCL1 and CXCL8 and rather high levels of CXCL2 and CXCL3 chemokines." (PMID 28129639, 2017). "We also noted that the absence of Mcpt4/Mcpt6/CPA3 was associated with alterations in the expression a range of other genes of potential impact on the melanoma colonization processes: HGF, MMP2, FGF, CXCL2." (PMID 28212574, 2017). "Malignant melanoma expresses and secretes various CXC chemokines, including CXCL1, CXCL2, CXCL3 (GRO family chemokines) and CXCL8 (IL-8)." (PMID 28129639, 2017). "The key chemokines involved in TAN recruitment to murine melanoma signal via the CXCR1 and CXCR2 axes, including CXCL1, CXCL2, CXCL6 and CXCL8." (PMID 28435677, 2017). "HVJ-E combined with CXCL2 resulted in increased IFN-γ expression in the Elispot assay, indicating an increase in cytotoxic T lymphocytes (CTLs) against B16-F10 melanoma cells." (PMID 27259252, 2016). "The reduction in the levels of chemokines CXCL1, CXCL2 and CXCL3 in melanoma results in a decrease in tumor angiogenesis and tumor growth, suggesting the importance of these chemokines in angiogenesis." (PMID 24259307, 2013).